PKD1 (polycystin 1, transient receptor potential channel interacting)
Diseases named in the same sentence as PKD1 in open-access papers (continued):
Sharing a sentence is not in itself a finding about the gene and the disease.
autosomal dominant polycystic kidney disease (continued). "Autosomal dominant polycystic kidney disease (ADPKD) is the most common inherited kidney disorder, typically presenting in adulthood and most often caused by PKD1 or PKD2 mutations." (PMID 41450889, 2025). "Autosomal Dominant Polycystic Kidney Disease (ADPKD) is the most common genetic kidney disorder, predominantly caused by pathogenic variants in the PKD1 and PKD2 genes." (PMID 40268755, 2025). "For example, it has been shown that Persian cats are susceptible to developing autosomal dominant polycystic kidney disease (ADPKD) (MONDO:1011054) due to a variant in the polycystin 1, transient receptor potential channel interacting gene (PKD1, NCBIGene:100144606)." (PMID 38883236, 2025). "Autosomal dominant polycystic kidney disease (ADPKD) is the most common monogenic inherited nephropathy, caused by mutations in either the PKD1 or PKD2 gene, which encode polycystin-1 and polycystin-2, respectively." (PMID 41195291, 2025). "Inactivation of PKD1 results in autosomal dominant polycystic kidney disease, a very common disorder characterized by the accumulation of fluid-filled cysts and end-stage renal disease." (PMID 39747084, 2025). "Autosomal dominant polycystic kidney disease (ADPKD), primarily caused by mutations in the PKD1 or PKD2 gene, is among the most common hereditary kidney diseases worldwide and is associated with significant extrarenal manifestations, including cardiovascular disease." (PMID 40980664, 2025). "Pathogenic variants in PKD1 and PKD2 genes are the leading cause of autosomal dominant polycystic kidney disease (ADPKD), the most common type amongst PKDs, accounting for more than 90% of affected individuals." (PMID 41255498, 2025). "Autosomal Dominant Polycystic Kidney Disease (ADPKD) is caused by mutations in PKD1 or PKD2 genes, encoding polycystin-1 (PC1) or polycystin-2 (PC2), respectively, characterized by excessive cell proliferation and fluid secretion, resulting in renal cyst formation and growth." (PMID 41465431, 2025). "Autosomal dominant polycystic kidney disease (ADPKD) is the most common hereditary kidney disease, caused by mutations in either the PKD1 or PKD2 gene, and is characterized by the development of multiple renal cysts." (PMID 41425591, 2025). "Autosomal Dominant Polycystic Kidney Disease (ADPKD) is the most common inherited kidney disease, caused by pathogenic variants in PKD1, PKD2, or rarely other genes." (PMID 40783883, 2025). "Until recently, the role of PKD1 and PKD2 has been associated with the pathogenesis of the kidney since mutations in these genes cause autosomal dominant polycystic kidney disease (ADPKD)." (PMID 40299470, 2025). "Autosomal dominant polycystic kidney disease (ADPKD) is caused by mutations in PKD1 or PKD2, which encode polycystin-1 (PC1) and polycystin-2 (PC2), respectively." (PMID 40763312, 2025). "Mutations in PKD1 and PKD2 cause autosomal dominant polycystic kidney disease (ADPKD), the most common renal genetic disease, leading to the dysregulation of renal tubules and the development of cystic growth that compromises kidney function." (PMID 40722835, 2025). "Renal polycystins (PKD1 and PKD2) are ion channel subunits with associated genetic variants that cause autosomal dominant polycystic kidney disease (ADPKD) (1, –3)." (PMID 40504156, 2025). "However, cases of adult CHF with autosomal dominant polycystic kidney disease (ADPKD) caused by PKD1 gene mutation are extremely rare." (PMID 38384417, 2024). "PKD1/2, involved in CHD, are the pathogenic genes for autosomal dominant polycystic kidney disease (ADPKD)." (PMID 38918687, 2024). "Autosomal dominant polycystic kidney disease (ADPKD) stands as the most prevalent genetic cystic kidney disorder, with 85% of cases attributed to mutations in the PKD1 gene on chromosome 16 and 10% to mutations in the PKD2 gene on chromosome 4." (PMID 38592079, 2024).
autosomal dominant polycystic kidney disease (continued). "For example, mutations in the PKD1 and PKD2 genes are the main cause of autosomal dominant polycystic kidney disease (ADPKD), which leads to cyst formation and gradual kidney failure." (PMID 39728069, 2024). "Mutations in PKD1 and PKD2 cause autosomal dominant polycystic kidney disease (ADPKD), which is characterized by the formation of fluid‐filled cysts in the kidney." (PMID 38561249, 2024). "RGLS4326 is specifically developed to inhibit the pathological functions of the miR-17 family in autosomal dominant polycystic kidney disease (ADPKD), one of the most frequent monogenic disorders, caused by mutations in the PKD1 or PKD2 gene and for which therapeutic options are limited." (PMID 38338746, 2024). "Patients with TSC2/PKD1 contiguous gene syndrome develop early-onset polycystic kidney lesions, which tend to grow more rapidly than those in classical autosomal dominant polycystic kidney disease." (PMID 39323690, 2024). "Autosomal dominant polycystic kidney disease (ADPKD) is the most common renal genetic disorder caused mainly by mutations of the PKD1 or PKD2 gene, which code for polycystin-1 (PC1) or polycystin-2 (PC2), respectively." (PMID 38912583, 2024). "A recent evaluation of the role of palmitoylation in kidney diseases revealed that protein palmitoylation is critical for the localization and expression of PKD1 (Polycystin 1), which plays a vital role in autosomal dominant polycystic kidney disease." (PMID 39598479, 2024). "Autosomal Dominant Polycystic Kidney Disease (ADPKD) is primarily caused by mutations in the PKD1 (85%) or PKD2 gene (15%), which affect the glycoproteins polycystin 1 (PC1) and polycystin 2 (PC2), respectively." (PMID 38671609, 2024). "Autosomal dominant polycystic kidney disease (ADPKD), one of the most common genetic diseases in humans, is caused by mutations in either PKD1 or PKD2, two genes encoding polycystin-1 (PC1) and polycystin-2 (PC2, or TRPP2) protein, respectively." (PMID 37028763, 2023). "Autosomal dominant polycystic kidney disease (ADPKD) is the most common monogenic-inherited kidney disease, caused primarily by mutations in either PKD1 (85%) or PKD2 (15%), with an estimated incidence of ~1 in 1000." (PMID 36766548, 2023). "Autosomal dominant polycystic kidney disease (ADPKD) is the most common inherited KD, due to mutations in the polycystic kidney disease 1 and 2 (PKD1 or PKD2) genes." (PMID 37762196, 2023). "Autosomal dominant polycystic kidney disease (ADPKD), caused predominantly by mutations to PKD1 or PKD2, is the most common monogenic kidney disease." (PMID 37345660, 2023). "Contiguous deletion of TSC2/PKD1 was found in one individual, who presented with renal cysts at age 6 months, hypertension at 14 months, and developed a clinical course akin to autosomal dominant polycystic kidney disease." (PMID 37386496, 2023). "Autosomal dominant polycystic kidney disease (ADPKD) is one of the most common human monogenic diseases and is mainly caused by mutations in PKD1 or PKD2." (PMID 38066436, 2023). "Autosomal dominant polycystic kidney disease (ADPKD) is an inherited cystic pathology consequent to mutations in the multipass transmembrane proteins polycistin-1 and polycistin-2, encoded respectively by Pkd-1 and Pkd-2 genes." (PMID 37842748, 2023). "Autosomal dominant polycystic kidney disease (ADPKD) is the most common hereditary kidney disease, affecting approximately 1:800 individuals; it is mainly due to mutations in two genes: PKD1 and PKD2." (PMID 37681898, 2023). "Inhumans, dysfunction of PKD2 or its most common interacting partner PKD1 leads to nearly all cases of Autosomal Dominant Polycystic Kidney disease (ADPKD)." (PMID 35359441, 2022). "Autosomal dominant polycystic kidney disease (ADPKD) is the commonest life-threatening hereditary disease, most of which is caused by a mutation in either the PKD1 or PKD2 gene." (PMID 35159216, 2022).
autosomal dominant polycystic kidney disease (continued). "Autosomal dominant polycystic kidney disease (PKD) is commonly inherited as a heterozygous, loss-of-function mutation in either PKD1 or PKD2, which encode the proteins polycystin-1 (PC1) or polycystin-2 (PC2), respectively." (PMID 36564419, 2022). "Autosomal dominant polycystic kidney disease (ADPKD) is an inherited kidney disease caused by mutations in polycystic kidney disease 1 gene (PKD1) and/or PKD2, whereby PKD1 mutations lead to the most severe ADPKD manifestations." (PMID 36614108, 2022). "Autosomal dominant polycystic kidney disease (ADPKD) affects approximately 12 million people worldwide and is mostly due to inherited mutations in either PKD1 or PKD2 genes." (PMID 36293397, 2022). "Autosomal dominant polycystic kidney disease (ADPKD) is the most common form, afflicting approximately 1 in 1,000 people and is caused by mutations in the transmembrane proteins polycystin-1 (Pkd1) and polycystin-2 (Pkd2)." (PMID 35253003, 2022). "Autosomal dominant polycystic kidney disease (ADPKD) is a genetic disorder, which is caused by mutations in the PKD1 and PKD2 genes, characterizing by progressive growth of multiple cysts in the kidneys, eventually leading to end-stage kidney disease (ESKD) and requiring renal replacement therapy." (PMID 35847973, 2022). "The seven probands with inherited renal structural abnormality included four autosomal recessive polycystic kidney disease (ARPKD) caused by the compound heterozygous variants in PKHD1 and three autosomal dominant polycystic kidney disease (ADPKD) caused by the heterozygous variants in PKD1." (PMID 36685964, 2022). "Another negative regulator of STIM1 is the fragment P100 of polycystin-1, the gene product of PKD1 whose mutations result in autosomal dominant polycystic kidney disease (ADPKD)." (PMID 34685498, 2021). "Autosomal dominant polycystic kidney disease (ADPKD), occurring due to PKD1 and PKD2 mutations, have been identified more than three decades ago." (PMID 34440002, 2021). "The polycystic kidney disease (PKD) protein family is named after the founding member, PKD1, which was originally identified in linkage studies for autosomal dominant polycystic kidney disease (ADPKD), one of the most common human genetic diseases." (PMID 34381056, 2021). "Autosomal Dominant Polycystic Kidney Disease (ADPKD) is a major renal pathology provoked by the deletion of PKD1 or PKD2 genes leading to local renal tubule dilation followed by the formation of numerous cysts, ending up with renal failure in adulthood." (PMID 34124016, 2021). "Autosomal-dominant polycystic kidney disease (ADPKD) is considered the most common monogenic-inherited kidney disease, mainly caused by mutations in either PKD1 (~85%) or PKD2 (~15%) with an incidence estimated to be ~1 in 10001." (PMID 34315885, 2021). "Autosomal dominant polycystic kidney disease (ADPKD), as one of the most common inherited kidney diseases, is caused by mutations of PKD1 or PKD2 gene." (PMID 33809516, 2021). "In autosomal dominant polycystic kidney disease (ADPKD), the majority of mutations occur in PKD1 and PKD2, which encode polycystin 1 and polycystin 2, which form a complex and function at the primary cilium." (PMID 34095126, 2021). "Autosomal dominant polycystic kidney disease (ADPKD), the most common inherited CKD, mainly results from PKD1 mutations." (PMID 32849923, 2020). "The utilized TSC2 probemix contained one probe (exon 40) for the TSC2-adjacent gene, PKD1 (polycystic kidney disease 1, MIM *601313), whose mutation cause autosomal dominant polycystic kidney disease (ADPKD, MIM#173900)." (PMID 32313033, 2020). "In particular, fibrocystin (PKHD1) is involved in autosomal recessive polycystic kidney disease (ARPKD), while polycystin-1 (PKD1) and polycystin-2 (PKD2) are implicated in autosomal dominant polycystic kidney disease (ADPKD)." (PMID 33339422, 2020).
autosomal dominant polycystic kidney disease (continued). "For instance, it has been known that the PKD1 and PKD2 genes underlying autosomal dominant polycystic kidney disease (ADPKD) play a role in the male reproductive system." (PMID 32752000, 2020). "Autosomal dominant polycystic kidney disease (ADPKD), a common of monogenetic disorder caused by the polycystic kidney disease-1 (PKD1) or PKD2 genes deficiency." (PMID 31907669, 2020). "For instance, the onset and progression of autosomal dominant polycystic kidney disease (ADPKD) is commonly explained as an effect of the dysregulated expression of the PKD1 or PKD2 genes." (PMID 30692602, 2019). "Pkd1+/− mice and patients with autosomal dominant polycystic kidney disease have endothelial eNOS/NO dysfunction." (PMID 31344780, 2019). "Autosomal dominant polycystic kidney disease (ADPKD), caused by mutations in either PKD1 or PKD2, is one of the most common monogenetic disorders and the leading genetic cause of end-stage renal disease (ESRD) in the United States1–3." (PMID 30760828, 2019). "For example, Polycystin 1 (PKD1), responsible for autosomal dominant polycystic kidney disease, has traditionally been challenging to analyze with NGS or Sanger sequencing because of its high GC-content, large size and homology with pseudogenes." (PMID 31134132, 2019). "Polycystin-1 (PC-1) and 2 (PC-2) are the products of the PKD1 and PKD2 genes, which are mutated in Autosomal Dominant Polycystic Kidney Disease (ADPKD)." (PMID 31719603, 2019). "Mutations in the polycystins (PC), i.e. polycystic kidney disease 1 (PKD1) and PKD2, cause autosomal dominant polycystic kidney disease in humans." (PMID 29502161, 2019). "For example, mutations of PKD1 and PKD2 are causal for autosomal dominant polycystic kidney disease, with kidney ECs and tubular cells of patients evidencing deficient calcium and NO responses and increased proliferation." (PMID 31344780, 2019). "Polycystic kidney disease 1 (PKD1) and PKD2 are genes responsible for encoding polycystin 1 and polycystin 2 respectively, and loss-of-function of PKD1 and PKD2 genes can result in autosomal dominant polycystic kidney disease in subsequent generations." (PMID 31757932, 2019). "Polycystin-1 (PC1), the protein product of PKD1, mutated in the common ciliopathy autosomal dominant polycystic kidney disease (ADPKD), has been shown to interact with tuberin." (PMID 29473038, 2018). "Autosomal dominant Polycystic Kidney Disease (ADPKD) is a monogenic disorder, caused by loss-of-function mutations in either the PKD1 (in ∼85% of cases) or PKD2 (in the remaining ∼15%) genes." (PMID 30480096, 2018). "For example, PKD1 forms a complex with PKD2 and mutations in either of these proteins cause Autosomal Dominant Polycystic Kidney Disease (ADPKD), which is the most frequent potentially-lethal single-gene disorder in humans." (PMID 28271061, 2017). "Molecular diagnostics of autosomal dominant polycystic kidney disease (ADPKD), which is the most common inherited kidney disease, relies on mutation screening of PKD1 (16p13.3; OMIM ID: 601313) and PKD2 (4q21; OMIM ID: 173910)." (PMID 28604601, 2017). "Polycystin-1 (PC-1) is a large plasma membrane receptor, encoded by the PKD1 gene, which is mutated in most cases of Autosomal Dominant Polycystic Kidney Disease (ADPKD)." (PMID 25947155, 2015). "In the case of a germline PRKCSH mutation in ADPLD, the second hit could involve a somatic PRKCSH or SEC63 mutation on the other allele, or somatic hits on genes implicated in Autosomal Dominant Polycystic Kidney Disease (ADPKD), such as PKD1 and PKD216." (PMID 26671672, 2015). "Polycystin-1(PC1), encoded by polycystic kidney disease gene 1 (PKD1), has been identified in patients with autosomal dominant polycystic kidney disease (ADPKD)." (PMID 24618832, 2014).
autosomal dominant polycystic kidney disease (continued). "During mutation screening in autosomal dominant polycystic kidney disease, we identified in mononuclear cells (PBMC), an alternative splicing event on the exon 30 of PKD1 gene, the gene implicated in this disease." (PMID 24358217, 2013). "Autosomal dominant polycystic kidney disease (ADPKD), the most common form of PKD, is caused by mutation of PKD1 or PKD2, which encode the proteins polycystin-1 or polycystin-2, respectively." (PMID 23536832, 2013). "Mutations of the human genes encoding the polycystins (PKD1 and PKD2) cause autosomal-dominant polycystic kidney disease (ADPKD), the most frequent polycystic kidney disease in adults, leading to end-stage renal disease in adulthood." (PMID 22701722, 2012). "Although polycystin-1 (PC1), encoded by the Pkd1 gene, and Polycystin-2 (PC2), encoded by the Pkd2 gene, are mutated in autosomal dominant polycystic kidney disease, loss of polycystin function in mice also causes a severe skeletal phenotype." (PMID 21151991, 2010). "Autosomal dominant polycystic kidney disease (ADPKD) is the most common form of cystic disease, with a frequency of 1 in 800 live births and is caused by mutations in the PKD1 gene on chromosome 16 or the PKD2 gene on chromosome 4." (PMID 18810502, 2010). "Notably, the role of polycystins in primary cilium and kidney development has been largely studied, showing as PKD1 and PKD2 mutations result in the autosomal dominant polycystic kidney disease." (PMID 40282211, 2025). "Examples include large deletions encompassing TSC2 and PKD1, resulting in a combined phenotype of tuberous sclerosis complex and autosomal dominant polycystic kidney disease, as well as deletions involving COL4A5 and COL4A6, which cause Alport syndrome with diffuse leiomyomatosis." (PMID 41303235, 2025). "Polycystin-1, the product of PKD1, is mostly studied in the context of autosomal dominant polycystic kidney disease (ADPKD), a hereditary genetic condition characterized by the growth of kidney cysts that replace the normal tissue, eventually leading to kidney failure." (PMID 41359183, 2025). "Our results suggest that guanine quadruplex DNAs provoke DNA breaks in PKD1, providing a potential mechanism for cystogenesis in autosomal dominant polycystic kidney disease specifically and for the inactivation of guanine quadruplex-rich tumor suppressors generally." (PMID 39747084, 2025). "Two males were incidentally diagnosed with AS through genetic testing during screening for autosomal dominant polycystic kidney disease, with no pathogenic variants found in the PKD1 or PKD2 genes." (PMID 40806767, 2025). "Furthermore, TSC2 lies directly adjacent to PKD1, the gene responsible for autosomal dominant polycystic kidney disease (ADPKD), and TSC patients can have large genetic deletions that span both genes in a disorder known as TSC2/PKD1 contiguous gene syndrome." (PMID 38802873, 2024). "Additionally, ACs have been linked to autosomal dominant polycystic kidney disease (ADPKD), particularly when caused by pathogenic variants in the PKD1 gene, and a familial case of posterior fossa AC and polycystic kidney disease has been reported." (PMID 38052889, 2024). "Murine PKD1 knockout renal tubular cells seeded in silk-scaffolds filled with Matrigel and collagen hydrogels has been shown to reproduce morphological and functional abnormalities present in Autosomal Dominant Polycystic Kidney disease (ADPKD)." (PMID 36569770, 2022). "Consistent with the gene dosage effect hypothesis, renal cysts can arise in transgenic murine models overexpressing either PKD1 or PKD2, which are causal genes for autosomal dominant polycystic kidney disease (ADPKD)." (PMID 31979107, 2020). "Formation of renal cysts is the hallmark of autosomal dominant polycystic kidney disease (ADPKD), which is the most common ciliopathy and is mainly caused by mutations in the genes PKD1 and PKD2, which encode the proteins polycystin-1 (PC1) and polycystin-2 (PC2)." (PMID 31979260, 2020).